TEX50 (testis expressed 50)
Description:
Sperm membrane protein required for stability of the sperm acrosome after its formation in the testis. Essential for male fertility.
Gene: Protein-coding gene on chromosome 1 (173,635,338 to 173,637,130, forward strand). Ensembl gene ENSG00000232113.
Subcellular location: Membrane
Gene Ontology:
Cellular component: membrane
Genetic constraint (gnomAD): Loss-of-function variants: 3 observed, 8.28 expected, observed/expected ratio (o/e) 0.36, 90% interval 0.16 to 0.94. That is too few expected variants to judge how well the gene tolerates losing a copy. Missense variants: 153 observed, 195.21 expected, observed/expected ratio (o/e) 0.78, 90% interval 0.69 to 0.9. Synonymous variants: 59 observed, 70.75 expected, observed/expected ratio (o/e) 0.83, 90% interval 0.68 to 1.04.
Homologues: Orthologues: chimpanzee TEX50 (98% identical), macaque TEX50 (90% identical), dog TEX50 (66% identical), pig TEX50 (63% identical), rat Tex50 (60% identical), rabbit TEX50 (60% identical), mouse Tex50 (59% identical).